MTOR (mechanistic target of rapamycin kinase)
Diseases named in the same sentence as MTOR in open-access papers (continued):
Sharing a sentence is not in itself a finding about the gene and the disease.
tumor (continued). "Interestingly, as MDSCs rely on glycolysis for proliferation and their immunosuppressive activity by evading ROS-mediated apoptosis and enhancing mTOR pathway activation, it remains to be understood how MDSCs thrive with metabolic competition in glycolytic tumor environments." (PMID 33324565, 2020). "Altogether, these findings suggest that targeting glucose metabolism through the combined inhibition of the Rb/E2F/c-myc axis and the PI3K/AKT/mTOR signaling may contribute to the anti-tumor efficacy of palbociclib-PI3K/mTOR inhibitors combinations in MPM cells." (PMID 32708306, 2020). "Interestingly, mTOR has been shown to regulate this secretory response and consequently, mTOR inhibition in combination with chemotherapy or radiotherapy may suppresses this secretory program and its ability to promote tumor growth." (PMID 33105713, 2020). "Further, to investigate whether the anti-tumor effects of the combined treatment are mediated via the inhibition of the Akt/mTOR pathway, the phosphorylation pattern of the members of this pathway were analyzed in the HCC cells treated with BEZ235 and regorafenib for 48 h." (PMID 32466169, 2020). "Therefore, we investigate whether TTK protein regulates proliferation and apoptosis of tumor cells by modulating the Akt‐mTOR signaling pathway." (PMID 32530571, 2020). "Besides that, activation of this PI3K/Akt/mTOR signaling was usually followed by speedy growth and metastasis of tumors, and variation of its protein expressions was also indicative of tumor prognosis, which implied a linkage of SRPX2 with PI3K/Akt/mTOR signaling underlying tumorigenesis." (PMID 33336063, 2020). "While the PI3K/Akt/mTOR pathway is essential to immune cell maturation, the pathway also regulates expression of cytokines associated with recruitment of myeloid derived suppressor cells (MDSC) and regulatory T-cells as well as expression of PD-L1 on tumor cells." (PMID 32612958, 2020). "In addition, mTOR inhibition did not result in a counteracting phospho-Akt upregulation in these cells - a frequently observed resistance mechanism in tumor cells based on loss of the negative S6K feedback loop on IRS and PI3K." (PMID 33628728, 2020). "Interestingly, tumor cells in which the PI3K/Akt/mTOR pathway is dysregulated are more susceptible to the inhibition of mTOR, the downstream effector of this signaling pathway, than normal cells." (PMID 33718332, 2020). "Thus, we next sought to examine whether the inhibitory effect of EPS1-1 on tumor cells was mediated through the AMPK/mTOR signaling pathway." (PMID 31894839, 2020). "Intriguingly, our results imply that metabolic inhibitors might be most effective on those tumor cells that are otherwise therapy-resistant and that signs of mTOR signaling such as ULK1S757 phosphorylation are potential biomarkers for metabolically vulnerable tumors." (PMID 32943635, 2020). "Therefore, NEN cells may use mTOR drug-induced inhibition to induce autophagy, enabling tumour survival and development of escape mechanisms and mTOR resistance." (PMID 32114655, 2020). "Research shows that the PI3K/Akt activation of the mTOR signaling pathway can inhibit the apoptosis of cells, and the activation of PI3K can cause mutations in the normal Akt physiological function of the cells, and generate induced tumors, to suppresses tumor cell apoptosis." (PMID 32009955, 2019). "PTEN, the acronym for phosphatase and tensin homolog, is well known to function as a tumor suppressor gene by negatively modulating the phosphoinositide 3-kinase (PI3K)/v-akt murine thymoma viral oncogene homolog (Akt)/mammalian target of the rapamycin (mTOR) signaling pathway." (PMID 31540513, 2019). "Mir-99a might involve in tumor cell growth via regulating mTOR signaling." (PMID 31156552, 2019). "This may explain why, in the present study, the mTOR pathway expression within the tumour and not in the peritumour, was associated with HCC recurrence after LT." (PMID 30650598, 2019).
tumor (continued). "In keeping with these results, loss of specific tumor suppressors, such as promyelocytic leukemia protein (PML) or tuberous sclerosis proteins 1 and 2 (TSC1 and TSC2), has been shown to promote HIF-1α expression through suppression of hypoxia-induced inhibition of mTOR." (PMID 31530290, 2019). "In these tumour zones, the mammalian target of rapamycin (mTOR) is deactivated, which induces the autophagy process; conversely, autophagy deactivation is due to the reactivation of mTOR, so there exists an inversely proportional relationship between autophagy and mTOR." (PMID 30764513, 2019). "Therefore, we hypothesized that mTOR can play a regulatory role in controlling DC functions for enhancing the anti-tumor immunities of tumor-bearing hosts based on these evidences." (PMID 31052575, 2019). "Interestingly, tumor cells use the PI3K/Akt/mTOR signaling more than normal cells." (PMID 31557166, 2019). "Therefore, the use of mTOR blockers might be a rational approach when treating tumor patients using radiotherapy." (PMID 31929797, 2019). "However, under these conditions, not only might all mitochondrial OXPHOS, ROS generation, and mTOR activity be reduced but also necrotic cell death could be induced in hypoxic tumor tissues." (PMID 31929797, 2019). "Therefore, we hypothesised that the presence of tumour cells impaired the function of the mTOR pathway, which paralleled the effects attributed to increased phosphor-STAT3 levels in muscle cells." (PMID 30975087, 2019). "However, it is well known that sustained high AMPK activity may inhibit mTOR signaling in tumor growth." (PMID 31372520, 2019). "However, the expression of p-mTOR was increased in GLP-treated tumor samples." (PMID 31186406, 2019). "Here, we reported that PHN combined with autophagy blockers could produce anti-tumor effects at least partially through inhibition of autophagy via AMPK/mTOR/p70S6K signaling pathway, suggesting that combining use of PHN and an autophagy blocker might serve as a novel strategy against LSCC." (PMID 31147451, 2019). "Therefore, it might be difficult to expect the regulatory effects of mTOR inhibition on tumor antioxidant defense under extreme hypoxic conditions." (PMID 31929797, 2019). "Thus, ionizing radiation exposure could potentially increase radiation resistance in tumor cells through the mechanism of HER receptor activation of P13K/AKT/mTOR signaling, enhanced by PTP suppression, which plays a critical role in suppression of apoptosis." (PMID 31796844, 2019). "Furthermore, expression of four proteins is associated with tumor progression/high risk AML: DOT1L, mTOR, VIM and ZNF521, whereas the expression of six proteins is associated with tumor suppression/low risk AML: AEBP2, CAST, CBFB, LSP1, MAP1S and probably PCBP1." (PMID 30634713, 2019). "However, the subset of patients within Milan criteria experienced a delay in tumour recurrence, thus suggesting that the benefit of mTOR inhibitors may be restricted to a subgroup of patients still to be defined." (PMID 30650598, 2019). "Tumor PIK3CA mutations are not clear predictors of response to mTOR inhibition." (PMID 32923864, 2019). "Tumor organoids may be used to test the response of a given tumor to mTOR inhibitors." (PMID 31277692, 2019). "Therefore, combining rapamycin treatment with inhibition of RTKs could serve as a more effective strategy for inhibiting mTOR and tumor growth." (PMID 31817676, 2019).
tumor (continued). "Second, the PI3K/AKT/mTOR pathway, as a classic signaling pathway, widely exists in cells to promote cell survival, inhibit apoptosis, and prevent autophagy; this pathway is overactivated in various tumor tissues and facilitates carcinogenesis and angiogenesis." (PMID 31636809, 2019). "Thus, combining antiangiogenic compounds with mTOR inhibition might maximize inhibition of tumor angiogenesis." (PMID 31273555, 2019). "In addition, there may be an intense inflammatory reaction in the peritumour area driven by immune cells striving to counteract tumour spreading and which proliferation may be at least partially dependent from the mTOR pathway." (PMID 30650598, 2019). "Besides HIF-1, other pathways such as PI3K/Akt/mTOR are induced in tumor cells under hypoxia." (PMID 30987378, 2019). "Similarly, NSCLC PACs were divided into ‘MAPK/mTOR’ and ‘Null’ tumours." (PMID 31772293, 2019). "However, our cell culture methodology could have excluded other tumour clones that have a completely different molecular profile than the parental polyclonal line and show resistance to Buparlisib and/or mTOR inhibitors." (PMID 30736342, 2019). "Given the increased levels of AKT and the activation of the mTOR pathways in autophagy-deficient SW480 cells, we next determined whether inhibition of these pathways in conjunction with autophagy impairment could potentially slow tumor growth in our system." (PMID 31383875, 2019). "Thus, the inhibition of mTOR signaling might make tumor cells sensitive to radiation-induced ROS via the attenuation of NRF2-mediated antioxidant mechanisms under normoxic conditions." (PMID 31929797, 2019). "The mammalian Target of Rapamycin (mTOR) signaling network could regulate several physiologic and pathologic cellular processes, such as cell growth, proliferation, and survival, which is very important in tumor pathogenesis." (PMID 31179240, 2019). "In addition, the mTOR signaling pathway plays a vital role in tumor initiation and progression." (PMID 31058839, 2019). "In light of these data, mTOR inhibitor-based immunosuppression could be considered in patients with mTOR over-expression in whom adverse effects of these drugs may be overcome by a potential benefit of decreased tumour recurrence rates." (PMID 30650598, 2019). "Consequently, combining an mTOR inhibitor with an HDAC inhibitor may optimize an anti-tumor protocol." (PMID 31010254, 2019). "Thus, the inhibition of mTOR signaling in these tumor types could attenuate the expression of antioxidant enzymes and make tumors sensitive to ROS." (PMID 31929797, 2019). "Thus, a low dose of everolimus, a mammalian target of rapamycin (mTOR) inhibitor, was administered and the serum trough level of tacrolimus dropped to 2 ng/ml at a dose of 1 mg/day to prevent further development of neoplasms due to MTS." (PMID 31664942, 2019). "However, a significant association of mTOR expression with BCR was found for specimens from the malignant border of the tumor (B) but not the tumor center (A) (p = 0.0034 log rank)." (PMID 31885728, 2019). "Therefore, for patients being treated with some conventional anticancer drugs such as mTOR inhibitors, potentially induced PD-L1 on host immune cells may be a driving force that cannot be ignored in tumor immune escape." (PMID 29744030, 2018). "While mTOR has been recognized as a key driver of metabolic reprogramming in NK cells, the mechanisms by which mTOR regulates the metabolic system and NK cell effector responses in the tumor microenvironment are still largely unknown." (PMID 30467503, 2018). "Therefore, inhibiting mTOR may be a potential treatment to target the MBSCs, thus reducing the chances of tumor recurrence and therapy resistance." (PMID 29932116, 2018). "Finally, mTOR is also involved in the tumorigenesis process by altering the tumor microenvironment." (PMID 29351204, 2018). "Similarly, UBTOR depletion promoted tumor growth and mTOR signaling in a xenograft mouse model." (PMID 30080879, 2018).
tumor (continued). "The two drugs effectively controlled the tumor growth by blocking the β2-AR, and then consequently suppressing the expression of p-Akt, p-mTOR, Bcl-2, cyclin D1, HK2 and GLUT1, which indicated that propranolol could enhance the efficacy of vemurafenib, a member of TKIs." (PMID 29416656, 2018). "In our study, we confirmed that activation of AMPK/mTOR pathway in Rage ablation cells accounted for autophagy increase and proliferation impairment, which might explain the different relationship between autophagy and Rage in varied tumor cells." (PMID 29445087, 2018). "mTOR activation may play a role in several aspects of tumor initiation and progression." (PMID 29351204, 2018). "One study found that mTOR can regulate the degradation of extracellular matrix in cancer cells and influence the synthesis and secretion of matrix metalloproteinase; through this mechanism, this protein can also promote the invasion and metastasis of tumor cells." (PMID 29455668, 2018). "Also anti-PD-L1 mAbs may directly affect tumor cells by impacting tumor metabolism, reducing extracellular acidification, phosphorylation of mTOR, and glycolysis." (PMID 30108594, 2018). "In addition to mTOR inhibitors, tumor responses have been observed with the use of chemotherapy." (PMID 30285856, 2018). "Finally, it has been shown that the PI3K/AKT/mTOR signaling pathway is implicated in CSCs, and specifically in MBSCs, demonstrating that the inhibition of this signaling pathway reduces the MBSC population in the primary tumor culture." (PMID 29932116, 2018). "Additionally, mTOR repression was observed in drug treated tumor tissues." (PMID 29416762, 2018). "Thus, UBTOR depletion promoted tumor growth and mTOR signaling in the xenograft mouse model." (PMID 30080879, 2018). "Therefore, the combination of PD901 with AKT/mTOR inhibitors might be helpful to induce growth restraint and tumor regression in K-Ras/NICD mice and, possibly, human iCCA." (PMID 29348467, 2018). "While overexpression of p-S6 (Ser 235/236) was elevated in the two patients harbouring PIK3CA mutations, staining intensity of p-AKT, p-mTOR, p-S6 (Ser 235/236), p-S6 (Ser 240/244) and p-4EBP1 did not correlate across the tumours, indicating a complex mode of pathway activation." (PMID 29527009, 2018). "One potential explanation of these results demonstrating reduced survival when an mTOR inhibitor was added to the therapeutic regimen in GB could be protective effects of mTOR inhibition in the context of the tumor microenvironment that we have previously shown in cell culture models." (PMID 30129426, 2018). "The tumor-promoting effect of SH2B1 may be partially related the activations of Akt/mTOR/PTEN axis." (PMID 30202243, 2018). "Additionally, our study suggested that DANCR may regulate mammalian target of rapamycin (mTOR) expression through sponging miR‐496, thus modulating tumour growth." (PMID 29266795, 2018). "In addition, PI3K/AKT/mTOR/p70S6K signal pathway is the primary pathway that regulates autophagy when cells are exposed to certain conditions, such as starvation, oxidative stress, and tumor suppression." (PMID 29533017, 2018). "Desirably, mTOR inhibitors could inhibit the cell proliferation and reduce tumor cell volume." (PMID 30107845, 2018). "In addition, aerobic glycolysis in tumor cells promotes depletion of extracellular glucose and leads to dysfunction of TILs, while expression of PD-L1 in tumor cells leads to constitutive activation of the Akt/mTOR pathway." (PMID 28545581, 2017). "Moreover, genome sequencing of different regions of a human renal cell carcinoma revealed that a kinase domain mutation of mTOR was not present in every tumor region." (PMID 28280521, 2017). "In addition, although counterintuitive, emerging evidence suggests that mTOR inhibition may enhance the anti-tumor immune response." (PMID 28822012, 2017).
tumor (continued). "In conclusion, using an in vitro model of hypoxia, susceptible to mimic more closely the in vivo hypoxic tumor conditions, we depicted metabolomic profiles of response to the combination of rapamycin plus irinotecan, determined by a balance between upstream signals in MYC and mTOR/HIF-1/2α pathways." (PMID 29069732, 2017). "Thus, we demonstrated that PTRF negatively regulated the activation of the AKT/mTOR pathway, which may account for its tumor suppressive function." (PMID 27203393, 2017). "In addition, the mTOR pathway participates in tumor angiogenesis." (PMID 29104248, 2017). "Hence, targeting mTOR has the potential to slow down tumor progression." (PMID 29104248, 2017). "The observations that vascular mimicry correlates with mTOR expression and that rapamycin inhibits the expression of endothelial cell markers by tumor cells in vitro suggest that mTOR might further contribute to tumor blood supply by regulating vascular mimicry." (PMID 29104248, 2017). "In an array of studies recently conducted in our laboratories, we have clearly demonstrated that mTOR critically regulates multi-aspects of lal−/− MDSCs, including development, systemic expansion, trans-endothelial migration, immune suppression, and direct stimulation of tumor cell proliferation." (PMID 28415797, 2017). "Additionally, CYTOR could promote cell proliferation in vitro and tumor growth in vivo via activating the mTOR (mechanistic target of rapamycin) signaling pathway." (PMID 29108264, 2017). "Therefore, knockdown of PKM2 might attenuate the PI3K-Akt-mTOR signaling pathway, which induces autophagy activation and reduces the ability of tumor migration in GC cells." (PMID 28588255, 2017). "Finally, emerging evidence suggests that mTOR inhibitors might influence endothelial functions that participate in the tumor immune response." (PMID 29104248, 2017). "Continued surveillance is also required for possible longer-term concerns, such as suppression of fertility, proteinuria and hypophosphataemia, because patients with TSC may need indefinite mTOR inhibition due to the fact that tumours tend to regrow upon discontinuation." (PMID 28202028, 2017). "It has been documented that targeting AKT/mTOR signaling pathway may inhibit tumor growth and multiple inhibitors of this pathway have been developed and are being assessed in the laboratory and in clinical trials, including bevacizumab, gefitinib, and docetaxel." (PMID 28212545, 2017). "Interestingly, WISP1 was also shown to promote tumor cell metastasis by activating PI3K/Akt/mTOR signaling, which indicates that Talin-1 may promote cell adhesion via the classic mTOR pathway." (PMID 28099903, 2017). "Our model identified mutations in VHL (von Hippel-Lindau), PBMR1, BAP1, MTOR, ATM, SETD2, KDM5C and PTEN (phosphatase and tensin homolog), as well as copy number changes in MLH1, DUSP1 and RANDBP17 as significantly associated with various TF activity changes across tumours." (PMID 28139702, 2017). "Thus, to elucidate whether PI3K/AKT/mTOR pathway involved in DEK-induced tumor growth and progression in TNBC cells, we detected the expression level of PI3K/AKT/mTOR signaling pathway and downstream molecules by western blot." (PMID 29228721, 2017).